IL4 (interleukin 4)
Diseases named in the same sentence as IL4 in open-access papers (continued):
Sharing a sentence is not in itself a finding about the gene and the disease.
depression (continued). "In the PD group, IL-4 levels correlated with UPDRS II (r = 0.337), Non-Motor Symptom Scale (r = 0.354), Hamilton Depression Scale (r = 0.420) and PDQ-39 (r = 0.423) scores (p < 0.05)." (PMID 40672460, 2025). "The study found weak negative correlations between IL-4, BDNF, and neopterin levels and changes in PHQ-9 scores at both TP2 and TP3, suggesting a potential inverse relationship between these markers and depression symptoms." (PMID 39355088, 2024). "A negative correlation indicates that as IL-4 levels increase, the PHQ-9 score decreases slightly, suggesting a potential inverse relationship between IL-4 and depression symptoms." (PMID 39355088, 2024). "Rats with depression-like phenotype displayed increased levels of cytokines (IL-1β, IL-6, TNF-α, IL-4 and IL-10) in the PFC compared with sham-operated and rats without depression-like phenotype (P < 0.05) on day 21 after SNI surgery." (PMID 28600519, 2017).
parasitic infections (150 papers, 2006 to 2026). "M2 macrophages respond to type 2 inflammatory factors such as IL-4, which is believed to be associated with tissue repair and parasite infection." (PMID 39456703, 2024). "IL-4 induces the development of Th2 cells, which are implicated in immune responses against parasitic infections and exhibit anti-inflammatory properties." (PMID 38251210, 2024). "Given its association with alternative macrophage activation and parasitic infection, we next considered the potential role of IL-10 in IL-4/13 induced macrophage innate memory responses." (PMID 36173104, 2022). "The resistance in sheep during parasitic infection is typically associated with expression of IL-4, which mediates a Th2 type immune response." (PMID 32121527, 2020). "Humoral immunity is dependent on IL-4, as IL-4-, or IL-4R-deficient mouse models have impaired antibody production, high susceptibility to parasitic infection and diminished Th2 differentiation." (PMID 30842774, 2019). "IL-5 has been described as a Th2-cell cytokine whose expression is upregulated in inflammatory-associated conditions associated with parasitic infections, similar to IL-4 or IL-13, with secretion of IL-5 by astrocytes and microglia having been described." (PMID 26834537, 2015). "In contrast to Th1 responses, which promote IFN-γ–mediated killing of cryptococcus by macrophages, IL-4 produced in Th2 cells causes alternative activation of macrophages—typically a response to parasite infections—promoting fibrosis." (PMID 21253011, 2010). "The alternative pathway of macrophage activation, via IL-4, has been recently appreciated in many Th2-associated responses, such as parasitic infections and allergic inflammation." (PMID 19486531, 2009). "Elevated IL-4 levels may indicate an ongoing Th2 immune response, which is typically associated with certain parasitic infections and allergic reactions." (PMID 38251210, 2024). "Importantly, this phenomenon may explain why Th2-biased immune responses to parasite infections are highly associated with basophils that produce IL-4 upon exposure to cysteine proteases secreted from helminths." (PMID 29769546, 2018). "In this sense, it is possible that as parasitemia decreases, IL-4 expression also decreases, making it undetectable in our assay for monitoring its kinetics." (PMID 40743218, 2025). "Another theoretical concern for IL-4/13 and IL-5 blockers is helminth infections, since T2 immunity considerably protects against parasitic infections." (PMID 40843371, 2025). "ILC2s are stimulated by epithelial-produced cytokines IL-25, IL-33, IL-4 produced from basophils, secondary to parasitic infections or allergens, leading to the production of IL-4, IL-5 and IL-13." (PMID 39372419, 2024). "Eotaxin was positively correlated with NE and plasma RANTES (CCL5), IL-1α, and IL-2, and strongly negatively correlated with MPO, Mcpt1, parasitemia, plasma IL-4, ileal MCs, and FITC-dextran." (PMID 38780542, 2024). "Th2 cell differentiation, in the presence of IL-4, results in the production of IL-4, IL-5, and IL-13, thereby regulating both parasite infections and allergic inflammation." (PMID 38783005, 2024). "IL-4 and IL-13 play a critical role in allergic inflammation and parasite infection and act through the STAT6 signaling pathway." (PMID 39502090, 2024). "Similar to Th2 cells, ILC2s are elicited during parasitic infections and regulate tissue immunity and inflammation by producing Th2 cytokines (IL-4, IL-5- and IL-13) to recruit and activate eosinophils and alternatively activated macrophages." (PMID 39250522, 2024). "NK T cells (still present in Rag-1-/- mice) also produce IL-4 in response to certain parasitic infections." (PMID 39083533, 2024). "Polarization of M2 macrophages is stimulated by cytokines (such as IL-4, IL-10, and IL-13) and parasite infection." (PMID 39123188, 2024).
parasitic infections (continued). "After successfully controlling and clearing the parasitic infection, the Th2/IL-4 and Treg/TGF-β axis responses become dominant from day 4 to day 7, limiting inflammatory reactions and promoting tissue repair processes." (PMID 39830653, 2024). "IL-4 is also important for the defense response to parasitic infections and the inactivation of toxins." (PMID 38067030, 2023). "In this regard, IL4 has been shown to worsen the outcome of important diseases, such as cancer, virus, and parasitic diseases." (PMID 38010513, 2023). "It has been shown that MIF–CD74 activation is important for IL-4-induced M2 macrophage polarization in malignant diseases and parasitic infection through the TLR4-PI3K-Akt pathway." (PMID 36401289, 2022). "In contrast, alternatively activated M2 macrophages play a pivotal role in immune suppression, wound healing, and fibrosis, and are induced by parasitic infections, immune-suppressive cytokines (e.g., IL4, IL10, IL13), and glucocorticoids." (PMID 36552868, 2022). "Th1 subsets mainly express IFN-γ and IL-2, which are involved in cellular immunity to endogenous cell infection, while Th2 subsets express IL-4 and IL-10, which participate in allergic reactions and humoral immunity against parasitic infection." (PMID 36425118, 2022). "Basophils are the primary producers of IL-4 during parasite infection and aid in parasite clearance." (PMID 35820892, 2022). "Th2 cells are critical for the control of certain parasitic infections through the production of the clustered group of cytokines IL-4, IL-10 and IL-13." (PMID 35215986, 2022). "In participants with non-severe vivax malaria, our analysis revealed that only MDP levels of IL-1β and IL-4 were positively correlated with parasitemia." (PMID 34727121, 2021). "Effector B cells producing type 2 cytokines (B effector 2 [Be2]) have been shown to be important during parasitic infections, and early expression of IL-4 by these B cells promotes differentiation of type 2 CD4 T cells." (PMID 33383090, 2021). "In the host immune response to parasite infection, IL-4 is crucial to the protective immunity against extracellular parasite infection." (PMID 34488852, 2021). "Beyond sterile inflammation, IL-4 mediated macrophage responses are critical to control and clearance of numerous parasitic infections as well." (PMID 32431707, 2020). "During H. polygyrus infection AAM are induced by Th2 cells after epithelial damage alerts the immune system of parasite infection, resulting in IL-4 release and phenotypic shifts in both peritoneal and CNS macrophage populations." (PMID 33117327, 2020). "This apparently contradictory paradigm has been observed in previous studies when examining parasitic infections in IL-4−/− and IL-4R−/− mice." (PMID 33101712, 2020). "Collectively, IL-6, IL-18, IFN-γ, and IL-10 levels rose with parasitemia, while significant increases in IL-4 were biphasic, with a second peak occurring at day 10 p.i." (PMID 32958528, 2020). "Th1 cells mainly secrete cytokines such as IFN-γ and IL-2, which play an important role in antiviral and bacterial immune responses, while Th2 cells mainly secrete cytokines such as IL-4 and IL-10, which play a role in parasitic infection." (PMID 33294465, 2020). "Mucus production during parasite infections is under the immune control of type-2 cytokines, with interleukin-4 (IL-4), IL-13, and IL-22 altogether playing the major role in host protection." (PMID 31269896, 2019). "Regarding to IL-4, knockout mice displayed reduced acute phase parasitemia but showed subsequent increases in inflammation compared to non-depleted mice, indicating that this cytokine is necessary for tissue protection in the chronic phase." (PMID 29662478, 2018). "IL-4 is known as a marker of the Th2 immune response and has been reported as an important factor in protective immunity against parasite infections." (PMID 29848353, 2018).
parasitic infections (continued). "The increase in ileal MMCs was positively correlated with elevated parasitemia and IL-4 mRNA levels in the same tissue." (PMID 28428784, 2017). "Our interpretation of the effects of parasitic infection is that production of IL-4 and IL-5 by the activated Th2 cells and ILC2 accelerates the induction of autoantigen-specific Treg that express Il5ra, which in turn, reduced the severity of EAE." (PMID 29163523, 2017). "Other work in mouse macrophages showed that KDM6B can be upregulated by IL-4 in a STAT-6-dependent manner and that it is essential for IL-4 induced polarization in vitro and in response to certain kinds of parasitic infection in vivo." (PMID 28228757, 2017). "As parasitemia worsened from days 0 to 7, the concentrations of IL-12p70, IL-10, and IL-4 in the supernatant increased in the BMSA vaccinated group, although the concentrations of IL-2, IFN-γ, and IL-17 decreased." (PMID 29312230, 2017). "With parasitic infection and rIL-5 therapy, these autoantigen and IL-4 activated Treg were further expanded, respectively, by parasite infection-induced host type-2 response producing IL-5 or by administered IL-5." (PMID 29163523, 2017). "The modeling identified IL-4, IL-10, IL-12, and IFN-γ as the strongest mediators between infection status and parasitemia, with paired contrasts from the analysis indicating that IL-4 had the largest mediational effect." (PMID 27418744, 2016). "Parasitemia was significantly correlated with the following cytokines, in order of strength of association: IL-10, IL-12, TNF-α, IFN-γ, IL-1β, IL-6, IL-5, IL-2, IL-4, and IL-7." (PMID 27418744, 2016). "In agreement with the induced expression in vivo by viral and parasitic infection, the expression of trout IL-4/13B paralogues is induced in antigen presenting cells (ie the primary HK macrophages) by PAMPs." (PMID 26870894, 2016). "The bootstrapped paired contrasts from the analysis indicated that IL-4 had the greatest mediational effect between infection status and parasitemia." (PMID 27418744, 2016). "The Pearson correlations, used to load the mediation model, showed an inverse association between IL-4, IL-12, and IFN-γ, and parasitemia and a positive correlation between IL-10 and parasitemia." (PMID 27418744, 2016). "Although the constitutive expression level of IL-4/13B1 and B2 isoforms are lower compared to that of IL-4/13A, they are the major isoforms that are highly induced by viral and parasitic infection in vivo and by PAMPs in primary macrophages." (PMID 26870894, 2016). "IL4, IL12B, LTA, NCR3 have either been linked to mild malaria or parasitemia, alleles in these genes have been associated with these phenotypes." (PMID 25887595, 2015). "The observation that TFH cells produce IL-4 after parasite infection was confirmed by several studies." (PMID 24655429, 2014). "For instance, γδ T cells showed a Th1 effect by generating IL-2 and INF-γ when bacterial infection occurred inside cells; but showed a Th2 effect by stimulating B cells with IL-4 and IL-5 with extracellular parasite infection." (PMID 24460842, 2014). "The results from many studies have clearly identified IL-4/IL-5/IL-10 as important regulatory cytokines in parasitic infections, such as infection by Schistosoma mansoni in mice and humans, Schistosoma haematobium, Trichuris muris, and Trichinella spiralis." (PMID 24637903, 2014). "Instead, mice lacking integrin αvβ8 expression on DCs displayed an early increase in production of the protective type 2 cytokine IL-13 by CD4+ T-cells, and inhibition of this increase by crossing mice to IL-4 knockout mice restored parasite infection." (PMID 24098124, 2013). "TH2 cells are essential for the control of certain parasitic infections and mediate host defense against extracellular parasites through the production of interleukin 4 (IL-4), IL-5, and IL-13." (PMID 24130558, 2013).
parasitic infections (continued). "YM1, whose function is poorly understood, exists as a secretory protein transiently expressed in microglia/macrophages during hematopoiesis, during parasitic infection or after interleukin-4/interleukin-13 cytokine stimulation." (PMID 20846376, 2010). "In contrast to classically activated macrophages (M1), M2 are induced by Th2 cytokines IL-4 and IL-13, that are prevalent at parasitic infections and in wound settings." (PMID 18945374, 2008). "The TH2 phenotype is featured in responses to parasitic infections and is prominent in allergic responses, with IL-4, IL-5, and IL-13 as abundant cytokines." (PMID 16396683, 2006). "However, one consideration is parasitic infections—often helminth—in which IL-4 and IL-13 cytokines play important roles in host defense." (PMID 40843371, 2025). "IL-4 can also promote B cell differentiation and the production of anti-parasite specific antibodies Ig G1 and Ig E, thereby exerting humoral immunity to control parasitic infections." (PMID 39858178, 2025). "IL-4, an essential member of the Th2 cytokine family, not only effectively stimulates B-cell proliferation but also promotes the conversion of immunoglobulins to IgE and IgG4, playing a crucial role in allergic reactions and parasitic infections." (PMID 39290695, 2024). "Parasite infections can elicit a type 1 immune response characterized by the elevation of T helper 1 (Th1) cytokines such as interferon-γ, or a type 2 immune response featured by the production of Th2 cytokines such as interleukin 4 (IL-4), IL-5, and IL-13." (PMID 39559705, 2024). "During parasitic infection, IL-4 and IL-13 induce the Gsdmc1-4 expression in the intestine." (PMID 39489845, 2024). "Moreover, data from parasite infection models indicate that IL-4 production by TFH cells not only requires B cells but is dependent on ICOS/ICOSL interactions within the B cell follicle." (PMID 37575256, 2023). "Notably, however, an increased level of IL-4 concomitantly with basophils infiltration upon parasite infection was observed, and basophils are known to be the major source of IL-4." (PMID 33919759, 2021). "IL-4 treatment has led to reduced parasitemia and decreased mortality." (PMID 34790829, 2021). "On the other hand, the main factor associated with non-severe infections was the parasitemia values, that correlated only with perturbation of inflammatory markers, such as IL-4 and IL-1β, with a relatively lower number of symptoms." (PMID 34727121, 2021). "The balanced state between Th1 and Th2 immune responses mediated by their representative cytokines IFN-γ and IL-4 respectively, could determine the immunity and pathogenesis during parasitic infection." (PMID 32120801, 2020). "During parasite infections both IL-4 and IL-13 are the major drivers of STAT6 translocation." (PMID 30619333, 2018). "IL-4 produced early in the response to parasitic infection may have contributed to the initial activation of antigen-activated Treg to induce expression of il5ra and subsequent dependence on IL-5." (PMID 29163523, 2017). "In addition, local IL-4-dependent macrophage proliferation was observed following parasite infections in mice." (PMID 27245778, 2016). "Cytokines with the greatest mediational impact on parasitemia were IL-4, IL-10, IL-12, and IFN-γ." (PMID 27418744, 2016). "Colony-stimulating factor 1 (CSF-1) was proposed as a protein necessary to regulate the number of tissue-resident macrophages; nevertheless, it has been shown that interleukin-4 (IL-4) plays a major role in favoring the local proliferation of macrophages in parasitic infections." (PMID 26074923, 2015). "During the chronic parasitic infection, IL-4 is indispensable for proliferation of Th2 and B cells." (PMID 26503442, 2015).